APOA1 (apolipoprotein A1)
Diseases named in the same sentence as APOA1 in open-access papers (continued):
Sharing a sentence is not in itself a finding about the gene and the disease.
Obesity (146 papers, 2010 to 2026). Accumulation of substantial excess body fat. "Studies have reported that genetic variations in APOA1 are associated with altered serum lipid levels, obesity, and insulin resistance." (PMID 41422312, 2025). "For the first time, obesity was associated with eF before T2D (p < 0.001), and perimenopausal age with apoA1 and haptoglobin increases (p < 0.0001)." (PMID 40428246, 2025). "While APOA1 possessed an anti-obesity effect which is associated with the increase of energy expenditure." (PMID 38665091, 2024). "Among them, obesity, BMI, body fat percentage, waist circumference, hip circumference, and resistin were risk factors, while apolipoprotein A1 (apoA1), high-density lipoprotein cholesterol (HDL-C), and nerve growth factor (NGF) were protective factors." (PMID 39050546, 2024). "In contrast to what was observed for infection, most comorbidities were risk factors for severity in both groups (p = 0.03 for obesity for the apoA1 group and p < 0.001 for all other statistically significant comorbidities)." (PMID 37372137, 2023). "Almost all comorbidities were risk factors for AKI in both groups (p = 0.002 for obesity in apoA1 and p < 0.001 for all other comorbidities in both groups)." (PMID 37372137, 2023). "A study associating SNPs in the ApoA1 gene and obesity with the risk of low HDL-C disease showed that participants with the rs670 G allele had a 1.46 times (OR) greater risk of low HDL-C disease compared with other alleles (95% CI: 1.118–1.915; p=0.005)." (PMID 35873099, 2022). "The results are in line with some previous studies which supports the association between ApoA1 gene, obesity and serum HDL-C levels." (PMID 28969676, 2017). "The APOA1 rs5069 A allele and AA genotype were associated with both obesity and T2DM." (PMID 41588446, 2026). "Importantly, data on the APOA1 (rs5069) polymorphism among Egyptian populations are limited, despite the high regional prevalence of obesity and T2DM and possible ethnic differences in allele frequency and metabolic response." (PMID 41422312, 2025). "In addition, there is a clear causal relationship between the ApoB/ApoA1 ratio and indicators related to glucose metabolism, obesity, and biological behavioral characteristics, serving as a mediating effect in CMD and related risk factor." (PMID 38310324, 2024). "Furthermore, inverse associations with incident DD were found for obesity among men, and ApoB/ApoA1 ratio among both sexes." (PMID 34282190, 2021). "Furthermore, an inverse association between obesity among men and DD, and also between ApoB/ApoA1 ratio and DD was found in both sexes." (PMID 34282190, 2021). "Interestingly, polymorphisms in the APOA1 gene have been associated with increased risk of developing obesity in humans." (PMID 33925284, 2021). "Specifically, this study aims to investigate association between ApoA1 gene and different types of obesity with the risk of serum low HDL-C level which may explain the deleterious role of obesity on HDL-C level." (PMID 28969676, 2017). "This is likely due to the much smaller sample size or alternatively, variation at the APOA1/C3/A4/A5 gene cluster may be the only genetic locus of the previously identified loci that associates with TG in extreme obesity." (PMID 25147553, 2014). "Obesity associates with both high triglyceride concentration and high apoB/apoA1 ratio." (PMID 25000408, 2014). "One speculated mechanism is that the effect of APOA5 gene variants on the risk of obesity might be attributed to this locus being in interaction with other obesity-risk genes, such as APOA1, APOC3 and APOA4 genes." (PMID 24903888, 2014). "This hypothesis generating study revealed that anti-apoA-1 IgG serum levels are associated to obesity and are independent predictors of CAC score >0 with a negative predictive value of 94%." (PMID 23258951, 2012).
Obesity (continued). "Therefore, the association between the ApoB/ApoA1 ratio and obesity, blood pressure, glucose, lipid, and IR parameters confirmed the potential role of the ApoB/ApoA1 ratio in the etiology of metabolic disorders and thus in the occurrence and development of MetS." (PMID 35069437, 2021). "However, knowing whether anti-apoA-1 IgG could be associated to obesity and predict a pathological CAC score (as a surrogate marker of coronary artery disease) in low cardiovascular risk patients has never been evaluated." (PMID 23258951, 2012). "Previous findings that several polymorphrism in apolipoprotein A1(ApoA-I) gene have been associated with obesity in Brazilian population and that body fat content was increased in apoA-I null mice model lead to query about the role apoA-I played in obesity development." (PMID 23039759, 2012). "Higher tertiles of LDLC, TC, TG, ApoB and ApoB: ApoA1, along with the lowest tertiles of HDLC and ApoA1 exhibited higher prevalence of Type II diabetes mellitus (all p ≤ 0.024) and overweight or obesity (all except for TC, p ≤ 0.024)." (PMID 40375303, 2025). "Anti-ApoA-1 antibodies (AAA1) are independently associated with cardiovascular disease, which remains a major cause of death in individuals with obesity." (PMID 39752005, 2025). "Higher insulin, C-peptide, and triglyceride levels, as well as lower HDL-C and ApoA1 levels with low-grade inflammation, accompany the obesity and type 2 diabetes, while abnormal HbA1c levels were measured accordingly only in patients with type 2 diabetes." (PMID 41226333, 2025). "Numerous studies have shown that ApoA1 has anti-obesity effects, and alterations in body fat mass were observed in mice when circulating ApoA1 levels were altered." (PMID 41422312, 2025). "In this regard, APOA1 abundance was found to be decreased in plasma from patients with obesity compared to healthy control individuals." (PMID 38703299, 2024). "Lifestyle interventions have been shown to decrease circulating apoB and increase circulating apoA1 in children with obesity and hypercholesterolemia." (PMID 38127151, 2024). "Some other reported lipoprotein abnormalities, including decreased levels of APOA1 in patients with obesity compared to lean individuals." (PMID 38703299, 2024). "The concentrations of triglycerides and ApoB were significantly higher, while the ApoA1 concentrations were significantly lower in individuals with obesity than those with overweight and normal BMI in both assessments." (PMID 39203787, 2024). "An interesting observation is that, in univariate MR analysis, an increase in obesity-related indicators significantly elevates the ApoB/ApoA1 ratio." (PMID 38310324, 2024). "Recently, the causal relationship between T2DM and the structure of HDL was investigated in a preclinical study assessing the effects of APOA1 and LCAT deficiency in diet-induced obesity and glucose homeostasis in mice." (PMID 37375802, 2023). "This study employed two-sample MR and MVMR analyses to demonstrate the independent causal effect of genetic reduction of ApoA-1 and LPA on the risk of insomnia while avoiding the confounding effect of obesity." (PMID 38087303, 2023). "Other factors that contribute to diet-induced obesity include APOA1, the most abundant protein of HDL, APOE, an important protein of HDL/LDL/VLDL, and the functional ligand of an LDL receptor." (PMID 37375802, 2023). "Our epidemiological results support the causal relationship between low ApoA1 as an independent risk factor of infection by SARS-CoV-2 in NAFLD patients with additive risks of T2DM and obesity." (PMID 35327501, 2022). "In conclusion, T2DM is associated with abnormal levels of A2M, ApoA1, and haptoglobin independently of NAFLD, age, sex, obesity, and COVID-19." (PMID 35327501, 2022).
Obesity (continued). "In this secondary analysis of a randomised controlled trial, we investigated the effects of 12-week dietary and exercise treatments on HDL-P subclass concentration, size and apoA1 in lactating women with overweight/obesity." (PMID 35067237, 2022). "T2DM, liver diseases, obesity and COVID-19 can impair the biogenesis of ApoA1, as well as its post-translational modifications, including oxidation, carbamylating, and glycation." (PMID 35327501, 2022). "A number of literatures have revealed that obesity increases the ApoB /ApoA1 ratio and that ApoA1 levels were positively associated with the risk of metabolically healthy obesity (MHO), but the ApoB /ApoA1 ratio is negatively associated." (PMID 34930329, 2021). "Many reports attribute more weight to the ApoB/ApoA1 ratio as an index of cardiovascular risk and it is considered as an effective predictor of CAD risk in overweight and obesity." (PMID 29544473, 2018). "In this study, we found that there existed interactive effects between ApoA1 rs670 and obesity on low HDL-C diseases." (PMID 28969676, 2017). "In our study, the serum apoA-1 and hepatic apoA-1 mRNA expressions were significantly increased in the obesity-insulin resistance rats after the FO intervention, and there was no statistical change between the CHF and PO." (PMID 27101976, 2016). "PCSK9 (TG, HDL cholesterol, ApoB and ApoA1/ApoB) was shown interactions with overweight/obesity to influence serum lipid levels." (PMID 26744084, 2016). "Defects in these genes are associated with various clinical conditions including obesity, type-2 diabetes (ADRB2), citrullinemia (SLC25A13), Tangier disease and systemic amyloidosis (APOA1)." (PMID 26030409, 2015). "Sik3, Apoa1, and Apoc3 have been shown to be associated with variations in total, HDL, LDL-cholesterol or triglyceride levels, and Cadm1 with obesity-related traits." (PMID 26555648, 2015). "Apolipoprotein A5 (APOA5) gene, located on chromosome 11 adjacent to APOA1/APOC3/APOA4 gene cluster with known functions in the metabolism of plasma lipids, also modulates the risk of obesity in a number of studies." (PMID 24903888, 2014). "The fact that the prevalence of serum anti-apoA-1 IgG positivity was raised in obese subjects to the same extend than what has been retrieved in other high cardiovascular risk settings, lend modest weight to this hypothesis and further links autoimmunity, cardiovascular diseases, and obesity." (PMID 23258951, 2012). "In the overweight and obesity group, the area under ROC curve (AUC) was the highest for apoB/apoA1 (0.655)." (PMID 23554700, 2011). "APOM, APOA2, APOC3, and APOA1, all apolipoproteins, were associated with lipid transport and involved in the PPAR signaling pathway and cholesterol metabolism, which played important roles in obesity development." (PMID 40438591, 2025). "It is known that obesity alters HDL metabolism, affecting ApoA-1, and this could explain the presence of anti-ApoA-1 antibodies and therefore increased CVD risk." (PMID 39752005, 2025). "Given that APOA1, APOC3, and APOA4 are genes associated with obesity and are grouped together in the same cluster as APOA5, it is possible that mutations in one gene within the cluster may be caused by genetic variations in another gene." (PMID 38867151, 2024). "However, after reverse MR analysis, the elevation of the ApoB/ApoA1 ratio seems to be correlated with the decrease in obesity-related indicators." (PMID 38310324, 2024). "The analysis revealed that HDL and apoA1 could serve as mediators when using obesity as an exposure." (PMID 39050546, 2024). "Moreover, LDL proteome of women with obesity showed higher levels of APOA1 than men with obesity, highlighting sex-related differences." (PMID 38703299, 2024). "Obesity can also encourage the progress of NSOM by reducing HDL cholesterol/apoA1." (PMID 39050546, 2024).
Obesity (continued). "Moreover, previously, it has been reported that plasma levels of APOA1 are inversely associated with some metabolic conditions, including T2DM, hyperlipidaemia, NAFLD and obesity." (PMID 38703299, 2024). "It is well known that obesity can modify the metabolism of high-density lipoproteins, including apolipoprotein A1, and could therefore increase AAA1 IgG levels over the positivity limit, indirectly enhancing cardiovascular disease risk." (PMID 36992254, 2023). "Finally, a recent work demonstrating a new source of ApoA1 for the liver through the portal vein directly from the intestine opens up many possible causal mechanisms with the risks of T2DM, liver diseases, obesity, and COVID-19." (PMID 35327501, 2022). "Apolipoprotein A1 and apolipoprotein B differences are affected by obesity." (PMID 36010152, 2022). "Further, mice studies implicate a potential anti-obesity effect of ApoA1." (PMID 33925284, 2021). "Previous studies have revealed that APOA1 and APOA2 genes were key regulatory factors of high density lipoprotein metabolism, which is significantly associated with obesity and body weight in humans; APOA1 and APOA2 have been considered as candidate genes for back fat thickness in pigs." (PMID 31009469, 2019). "We found a significant positive correlation between obestatin level and the levels of ApoA1 and large HDL subfractions, which may indicate a possible connection between the abnormal gastrointestinal response and decreased hepatic ApoA1 expression in obesity." (PMID 29506551, 2018). "Despite the size and detail of data in AMORIS, we only found a modest positive association between serum levels of glucose, apoB/ApoA-1 and BC severity, suggesting that these factors are not the main players in linking obesity and BC aggressiveness." (PMID 28376727, 2017). "This study aims to investigate association between six single nucleotide polymorphisms(SNPs) in APOA1 gene and types of obesity with the risk of low level HDL-C in the pastoral area of northwest China." (PMID 28969676, 2017). "The link between obesity and plasma lipid levels has been documented, nonetheless, the interactions of single nucleotide polymorphisms (SNPs) in ApoA1 gene and obesity on HDL-C level are limited." (PMID 28969676, 2017). "APOA1 gene may be associated with low HDL-C disease in the pastoral area of northwest China; obesity was the risk factor for low HDL-C disease; the low HDL-C disease is influenced by APOA1, obesity, and their interactions." (PMID 28969676, 2017). "Women may also have lower HDL cholesterol levels than men in response to obesity, so apoA1 levels may also differ between men and women in response to obesity." (PMID 21159217, 2011). "The positive correlation between the apoB/apoA1 ratio and hs-CRP and WBC was observed, so we think that apoB/apoA1 ratio was associated with not only lipid, but also with chronic low grade inflammation caused by obesity." (PMID 23554700, 2011). "Although the APOA1 variant may predispose to obesity, it does not appear to independently affect metabolic risk once obesity is established." (PMID 41422312, 2025). "However, their interaction with genetic variants such as APOA1 rs5069 in the context of obesity and diabetes is not well established." (PMID 41422312, 2025). "Therefore, obesity promotes NSOM by downregulating HDL-C/apoA1." (PMID 39050546, 2024). "Interactions between obesity and APOA1 polymorphisms may contribute towards diseases, rather than the individual effects of each factor." (PMID 28969676, 2017). "Therefore, the interactions between APOA1 rs670 and obesity might contribute to low HDL-C diseases, and might increase the risk of low HDL-C diseases." (PMID 28969676, 2017). "FBS: fasting blood sugar, FH: family history, TG: triglycerides, HDL: high-density lipoproteins, Tchol: total cholesterol, LDL: low-density lipoproteins, ApoA1: apolipoprotein A1, ApoB: apolipoprotein B, FTO: fat mass and obesity." (PMID 39925495, 2025).
Obesity (continued). "Within each obesity subgroup, one-way ANOVA was used to compare biochemical and metabolic indices across APOA1 genotypes." (PMID 41422312, 2025). "The MR analysis for mediation, obesity, and BMI reduced the production of HDL or apoA1, which served as protective factors affecting the development of NSOM." (PMID 39050546, 2024). "There were a total of nine positive factors, namely, obesity, BMI, body fat percentage, waist circumference, hip circumference, HDL cholesterol, apoA1, resistin, and NGF." (PMID 39050546, 2024). "In our study, subjects with obesity had higher concentrations of LDL, TG, and ApoB, and lower concentrations of HDL and ApoA1 in both assessments compared to subjects with overweight and normal BMI." (PMID 39203787, 2024). "Simultaneously, when obesity or BMI was used as the exposure and NSOM as the outcome, HDL cholesterol or apoA1 served as mediators through a two-step MR analysis." (PMID 39050546, 2024). "APOA1 is the precursor for the high-density lipoproteins that have known anti-inflammatory and antioxidant functions that are impaired in T2DM and obesity." (PMID 37895816, 2023). "In the subgroup comparison, patients with overweight/obesity were more likely male and had higher level of BMI, hipline, WHR, creatinine, FBG, HOMA-IR, and triglycerides and lower level of ApoA1 than patients of the other two subgroups." (PMID 34899591, 2021). "The cornerstone of obesity is increased adipose tissue content, and it is suggested that HDL and apoA1 regulate adipose tissue content (upper left part)." (PMID 33925284, 2021). "In their study, the positive associations between FT and FAI and the ApoB/ApoA1 ratio were no longer significant after adjusting for age and BMI together, which indicated that obesity might make more of a contribution to the increased ApoB/ApoA1 ratio than FT and FAI in adult PCOS patients." (PMID 35069437, 2021). "Our proteomics pathway analyses highlighted other proteins involved in lipoprotein metabolism (APOA1, BMP1, FABP3 and ANGPTL4) and that are key markers in obesity and NAFLD56–58." (PMID 32514005, 2020). "Besides, general obesity measured by BMI, abdominal obesity measured by WC, and abdominal obesity measured by WHR may serve as risk factors for low HDL-C disease; Finally, our results show that the low HDL-C disease is partly influenced by APOA1, obesity, and their interactions." (PMID 28969676, 2017). "Thus, in spite of the size and great detail of the data in AMORIS, we only found a modest positive association between serum levels of glucose, apoB/ApoA-1 and BC severity, suggesting that these factors are not the main players in the link between obesity and BC aggressiveness." (PMID 28376727, 2017). "A study of adolescent PCOS in our hospital confirmed that APOB/APOA1 is a good predictor of MS and that the ratio was higher in women with PCOS with obesity and a high free androgen index." (PMID 27902723, 2016). "Plasma levels of tumor marker CA19-9 and ApoA1, the major protein component of plasma HDL, were reported to be lower in obesity." (PMID 21203453, 2010). "BMI: body mass index, BP: blood pressure, FBS: fasting blood sugar, Tchol: total cholesterol, TG: triglycerides, HDL: high-density lipoproteins, LDL: low-density lipoproteins, ApoA1: apolipoprotein A1, ApoB: apolipoprotein B, FH: family history, FTO: fat mass and obesity." (PMID 39925495, 2025). "βGluCnCs intake for 12 weeks significantly increased the average change in the ApoA1/ApoB ratio in subjects with overweight and low-LDLc levels, but not in those with obesity and high-LDLc levels." (PMID 39408385, 2024). "Furthermore, during certain infections and chronic inflammation such as obesity, HDL composition and size also change, reducing particularly the content of certain apolipoproteins, such as APOA1 and APOE." (PMID 36969259, 2023).